VIM (vimentin)
Diseases named in the same sentence as VIM in open-access papers (continued):
Sharing a sentence is not in itself a finding about the gene and the disease.
tumor (continued). "Immunohistochemical studies were helpful in making a diagnosis, and several reports have suggested that spindle and epithelioid tumor cells show strong positive staining for SMA, desmin, and vimentin, and the absence of staining for cytokeratin as well as S-100 protein." (PMID 22248347, 2012). "The tumor cells showed intense reactivity for EMA and vimentin, but not for CK or S-100 protein." (PMID 21722387, 2011). "The tumor exhibits positivity for Vimentin, PR, and SMA, with negativity for PanCk, S100, Desmin, PSA, CK5/6, BCL2, MDM2, and Melan A. Additionally, the Ki-67 proliferation index is approximately 25 %, and CD34 highlights only the vascular walls without tumor cell positivity." (PMID 40686513, 2025). "All the five tumours in this study had a typical immunophenotype characterized by diffuse positivity for CK7 and negativity for CD117, and were also positive for PAX-8, E-cadherin, FH and SDHB, but negative for vimentin, CD10, P504s, CA9, CK20, TFE3, TFEB, HMB45, and ALK." (PMID 36816543, 2023). "Starting with the EpCAM, Vimentin and CD24 immunofluorescence grey levels for each nucleated cell, we used a supervised machine learning approach to predict whether an imaging field comes from a metastatic or non-metastatic tumour." (PMID 37975646, 2023). "Prevalent positive expressions of vimentin, AAT, or NSE do not define a specific lineage, and the tumor cells do not regularly exhibit neuroendocrine/ductal/adenocarcinoma elements, giving rise to the hypothesis of a totipotent cell origin that would further differentiate." (PMID 36292694, 2022). "Interestingly, the main cell type observed in the nonimmune compartment seven weeks after tumor induction, when tumor masses were fully developed, was a fibro/adipogenic-like population characterized by the expression of the Sca1, CD90.2, Vimentin, CD140α and CD34 markers." (PMID 33671425, 2021). "We found that among the top-ranked putative binding proteins of VAL, Vimentin, which has been well-recognized as an EMT marker and whose biological importance in tumor metastasis in a non-EMT context is largely unknown, was identified and validated to interact with VAL." (PMID 33046716, 2020). "Immunohistochemical staining showed that the tumor cells were negative for AE1/AE3, CK18, CK7, Hepatocyte Paraffin-1(Hep Par-1), Glypican-3 (GPC-3), Arginase-1 (ARG-1), CD56, Chromogranin A (CgA), Synaptophysin (Syn), Vimentin, and Carcinoembryonic antigen (CEA)." (PMID 31488173, 2019). "The differentiated tumour tissue (hepatoid and reserve cells) displayed strong membranous expression of high-molecular-weight cytokeratin (34βE12), low cytoplasmic expression for pan-cytokeratin (AE1/AE3), strong membranous E-cadherin expression and was negative for vimentin staining." (PMID 29144834, 2018). "Interestingly, no obvious difference was observed in vimentin and α-SMA positivity in the tumor stroma between tumors derived from EBC1 cells only and those derived from EBC1 cells with HFL1 or MRC5 cells at 8 weeks (data not shown) or at an even earlier time point (at 2 weeks) after inoculation." (PMID 28619066, 2017). "Immunohistochemical analysis of tumor cells indicated the following: HMB-45(+); vimentin(+); smooth muscle actin (SMA)(+); melan-A(+); CK(−); hepatocyte(−); Arg-1(−); GPC-3(−); CK7(−); CK19(−); CK20(−); S-100(−); CD34 blood vessel endothelium(+); and no exact tumor suppository." (PMID 26698563, 2015).
tumor (continued). "We have also shown that VIM-positive (CK19−/VIM+) CTC-enriched blood fractions, unlike CK19+/VIM− fractions, show elevated CXCR4 and uPAR levels, which might contribute to more aggressive tumor characteristics." (PMID 24709997, 2014). "We have not observed any statistically significant correlation between expression of VIM, TWIST1 or SNAI1 (analyzed together or separately) in CTCs-EBF and histological type of the tumor (ductal vs. lobular, p = 0.48) or molecular subtype of the primary tumor (p = 0.93, data not shown)." (PMID 24217115, 2013). "First we determined conditions under which normal epithelial cell layers could not be stained, but tumor cells with EMT could be, because undifferentiated layers (basal and parabasal) have been reported to express EMT-related genes including VIM." (PMID 21533028, 2011). "In univariate analyses, high tumour epithelial cell expressions of NF-κB p105 (P=0.02) and E-cadherin (P=0.03) were positive prognostic indicators for disease-specific survival (DSS), whereas high tumour epithelial cell expression of vimentin (P=0.001) was a negative prognostic indicator." (PMID 18854838, 2008). "Notably, lung cancer cells can induce vimentin expression and EMT in non-cancerous receptor cells by secreting exosomes, leading to their migration, invasion, and proliferation, which suggests that tumor cells can also induce peripheral cell EMT to promote tumor metastasis and invasion." (PMID 33224886, 2020). "Indeed, while these tumours showed high levels of H-RAS expression in comparison to adjacent normal tissue and were immunoreactive for the common mesenchymal marker VIMENTIN, the tumour cells did not stain for lineage markers including CD31, vWF, DESMIN, SMA, MYOD1 or MYOGENIN (last column)." (PMID 29731980, 2018). "In addition to existence of individual aneuploid CTCs and tumor CECs identified in carcinoma patients in this study, surprisingly, some aneuploid neoplastic cells and CTMs in cancer patients were found to have a non-reported, unique phenotype of CD31+/EpCAM+/Vimentin+." (PMID 28852197, 2017).
cancer (2,208 papers, 1988 to 2026). A tumor composed of atypical neoplastic, often pleomorphic cells that invade other tissues. "To investigate the functional implications of vimentin residue C328 in regulating EMT, cancer progression, and stemness, we expressed C328S vimentin in MCF-7 cells, a vimentin-deficient cell line commonly employed to study EMT." (PMID 40690373, 2025). "Vimentin is linked to cancer cell invasiveness and macrophage-secreted interleukin (IL)-35 and was reported to be overexpressed in a variety of cancers, including breast cancer and extrahepatic cholangiocarcinomas." (PMID 40457408, 2025). "EMT is characterized by enhanced cancer cell migration and invasion, typically marked by a loss of epithelial markers, like E-cadherin and a gain of mesenchymal markers such as N-cadherin, vimentin, and transcription factors like ZEB1." (PMID 40969596, 2025). "TGF-β-mediated EMT is a pivotal mechanism for NSCLC metastasis, where TGF-β induces loss of E-cadherin and upregulation of vimentin/N-cadherin, enabling invasion and cancer stem cell-like properties." (PMID 41301482, 2025). "We identified 6415 fibroblasts (DCN+ and/or VIM+ cells), clustering into four normal-associated fibroblast (NOFs) and five cancer-associated fibroblast groups (CAFs) based on their variable expressed genes." (PMID 40640495, 2025). "EMT-associated proteins like N-cadherin, vimentin, and Snail are critical markers of cancer metastasis." (PMID 40456746, 2025). "Key regulatory genes of EMT, such as E‐cadherin, fascin and vimentin have been identified in the pathogenesis of cancer and specifically HPV‐associated cancers." (PMID 40468102, 2025). "During EMT, the downregulation of E-cadherin and the upregulation of N-cadherin and Vimentin are strongly associated with the metastatic potential of cancer cells." (PMID 40777130, 2025). "Subsets of CTCs expressing cell surface markers such as CD90, EpCAM, CD133, and vimentin have been associated with cancer stemness and epithelial–mesenchymal transition (EMT), and reports on these subsets are increasing." (PMID 40940925, 2025). "Apart from vimentin, nestin has also been implicated in the disease progression of several cancer types, for example, breast, colorectal, uterine, gastrointestinal, and pancreatic cancers." (PMID 40282554, 2025). "To investigate the significance of C328 in EMT and cancer, we made a mutant encoding a C328S substitution in vimentin (C328S-VIM) and transduced in MCF-7 cells, which are devoid of endogenous vimentin, and are widely used as a model to study EMT." (PMID 40690373, 2025). "The overexpression of vimentin in cancer cells is closely linked to tumor growth, invasion, and poor prognosis." (PMID 40061451, 2025). "Vimentin is also implicated in several pathophysiological conditions such as cancer, autoimmune and inflammatory diseases, and infection, including wound healing and evading immune surveillance." (PMID 40051499, 2025). "HSP70 plays a role in cancer stemness by increasing the expression of cancer stemness-associated proteins (such as vimentin, N-cadherin, MMP-2, MMP-9, Snail, Slug, Twist, and others)." (PMID 41369386, 2025). "Cancer‐associated genes (VIM, IGHG1‐4, IGKC, IGHA1) were upregulated, and CPCAT data revealed correlations of IREB2 with IGHG1 and VIM, and CD27 with IGHG1." (PMID 41377765, 2025). "Several studies have demonstrated that the EMT-promoting function of vimentin is associated with poor clinical outcomes in various cancers, including leukemia, lung, neuroendocrine, gastric, colorectal, cervical, and breast cancer." (PMID 38915055, 2024). "Vimentin expression in CTCs is associated with increased metastatic potential and poor prognosis in these cancers, making it an important marker for monitoring disease progression." (PMID 39671082, 2024). "The upregulated expression of vimentin is associated with cancer metastasis, which involves the dissemination of cancer cells to distant locations in the body." (PMID 38685125, 2024).
cancer (continued). "This strong association between vimentin and the metastatic potential of cancer makes it a promising drug target for cancer therapy." (PMID 38915055, 2024). "The expression of vimentin was up regulated during EMT, and the overexpression of vimentin was associated with increased aggressiveness and metastasis in a variety of cancers." (PMID 38389041, 2024). "Although a large number of studies exist on the involvement of vimentin in cancer metastasis, studies focusing on the underlying mechanisms of its pro-metastatic function are limited." (PMID 38915055, 2024). "Elevated vimentin expression has been associated with metastatic potential and poor prognosis in various cancer types, including liver, breast, lung, and prostate." (PMID 39516342, 2024). "During EMT, cancer cells become elongated, which is associated with changes in cytoskeleton organization mainly via vimentin." (PMID 38791431, 2024). "In summary, cell-surface CK and VIM are associated with inflammatory events such as viral and bacterial infections, wound healing, and carcinoma." (PMID 39766058, 2024). "Cytokeratin 18 is an intermediate filament expressed in epithelial carcinoma and is diminished in basal subtypes, contrary to vimentin, which is implicated in the migration mechanism." (PMID 39201674, 2024). "The study also added that activation of the PDGF receptor causes reorganization of vimentin through the associated fibroblast cancer pathway of which α-SMA is a marker." (PMID 38046195, 2023). "Second - cells carry mesenchymal (Vimentin) and epithelial (E-cad) markers together, which is a hallmark of intermediate epithelial associated with stemness of cancer cells." (PMID 37006265, 2023). "Vimentin has also been implicated in many aspects of cancer initiation and progression, including tumorigenesis, EMT, and the metastatic spread of cancer." (PMID 37161053, 2023). "Cancer-associated fibroblasts (mCAF) in matrix expressing vimentin, SMA, COL3A, COL10, and MMP11 were predominant in HGSOC tumors and were capable of inducing EMT characteristics in HGSOC cells." (PMID 37090728, 2023). "EMT frequently results in the loss of (or a reduction in) E-cadherin and an increase in Vimentin and N-cadherin expression levels, a crucial mechanism in causing cancer to migrate and invade." (PMID 38003580, 2023). "The IAFs in a previous UC study expressed FAP, a marker of cancer-associated fibroblasts, and vimentin (VIM) as a marker validated experimentally in IAFs." (PMID 37834250, 2023). "Downregulation of the CDH1 gene and upregulation of CDH3, CDH2, and VIM in EMT is a hallmark of cancer metastasis." (PMID 37151391, 2023). "The disruption of vimentin leads to a decrease in cell migration and in the case of cancer cells, this decrease in migration is associated with a reduction of invasion of cancerous cells, giving it an antimetastatic activity." (PMID 37475865, 2023). "Contrastingly, the overexpression of N-cadherin and vimentin is associated with cancer aggressiveness." (PMID 38132928, 2023). "Vimentin overexpression has been associated with increased cancer cell growth, invasion, and migration, suggesting its potential application in cancer diagnosis and treatment." (PMID 36765679, 2023). "The EMT process (up-regulation of mesenchymal cell markers Vimentin and N-cadherin, loss of epithelial cell marker E-cadherin) allows cancer cells to migrate and invade more readily." (PMID 37105032, 2023). "Although this finding is affected by the included markers in our panel, we included aSMA, vimentin and collagen type 1, all typical markers for cancer associated fibroblasts (CAFs)." (PMID 37146405, 2023). "Here, we demonstrated that MP06 affects the transcription factors associated with EMT and affects vimentin expression, leading to inhibited cancer cell growth, invasion, and migration." (PMID 38132928, 2023).
cancer (continued). "The association between vimentin and cancer metastasis has been thoroughly studied and evaluated, leading to the acceptance and establishment of the use of vimentin as a marker for EMT-mediated metastasis." (PMID 36765706, 2023). "Vimentin has been implicated in wound healing, inflammation, and cancer, but its functional contribution to intestinal diseases is poorly understood." (PMID 35399505, 2022). "C15orf59-AS1 is the anti-sense RNA of C15orf59 (also known as INSYN1) gene and there are no reports of its expression in MCF-7 or any association with cancer or vimentin expression." (PMID 36552797, 2022). "The potential of this compound as a biomarker for resistant cancer cells also needs to be explored once it is more active in cells with high E-cadherin and low vimentin, both linked with cancer cell evasion and metastasis in PC." (PMID 36355012, 2022). "For instance, it remains understood if the acquired cell motility resembling cancer activity is associated with the aberrant expression of vimentin." (PMID 36387215, 2022). "The potential of using of vimentin as anti-cancer target is rather widely discussed, but recently it was shown that loss of vimentin increases cell motility through constricting spaces and small pores." (PMID 36278174, 2022). "In several cancers, loss of E-cadherin, enhanced expression of vimentin and Snail are known to induce EMT that contributes to migration, invasion and radioresistance." (PMID 36428597, 2022). "While mechanisms of transcriptional and translational regulation of vimentin during cellular events leading to cancer progression are diverse, overexpression of vimentin is associated with a more metastatic and invasive phenotype in these cancers." (PMID 35207438, 2022). "Activated fibroblasts co-expressing α-smooth muscle actin (SMA) and vimentin are associated with cancer; their extracellular matrix production/remodeling are different from that of resting fibroblasts." (PMID 35563747, 2022). "In the invasion front of carcinoma, there are CK and Vimentin highly expressed epithelial cancer cells, which have contact with cancer-associated fibroblasts (CAFs) and affect each other." (PMID 35269669, 2022). "Vimentin has been extensively studied in many other systems due to its role in cell migration associated with both embryogenesis and cancer invasiveness; however, it has been poorly studied in the context of pluripotency." (PMID 34996451, 2022). "Vimentin is a mesenchymal marker of the EMT process that its overexpression is associated with many cancers." (PMID 35449812, 2022). "Loss expression of E-cad was reported to associate with cancer metastasis, and VIM was reported to promote migration of cancer cells." (PMID 36072791, 2022). "Increased vimentin expression is associated with increased metastasis and poor prognosis in various cancers, such as colorectal cancer, oral squamous cell carcinoma." (PMID 36278174, 2022). "-Serum in media was reported to revert EMT, cancer stem cell, and hypoxia phenotype.-Spheroids cultured under hypoxia (1% O2) showed increased carbonic anhydrase IX, vimentin, N-cadherin, glioma-associated oncogene homolog 1, and decreased E-cadherin." (PMID 35992863, 2022). "Vimentin is a protein in the intermediate filament, which forms the cytoskeleton and is associated with cancer migration." (PMID 35978634, 2022). "In fact, WA caused accumulation of vimentin around the perinuclear wall followed by depolymerization of vimentin, causing rapid death of cancer cells." (PMID 34946778, 2021). "Given that the EMT process is associated with cancer cell migration and invasion, we tested the impact of altered circUBE2J2 expression on the relative levels of N-cadherin, Occludins, and Vimentin expression in HCC cells by western blot." (PMID 34686662, 2021). "On the contrary, N-cadherin and Vimentin are positively associated with increased cancer invasiveness." (PMID 34814869, 2021).